FOXM1 (forkhead box M1)
Diseases named in the same sentence as FOXM1 in open-access papers (continued):
Sharing a sentence is not in itself a finding about the gene and the disease.
meningioma (continued). "In humans, meningiomas from the Hypermitotic DNA methylation group have the worst outcomes and are distinguished by convergent genetic and epigenetic mechanisms that mis-activate the cell cycle, including enrichment of the FOXM1 gene expression program." (PMID 38376604, 2024). "Moreover, the knock down of FOXM1 in meningiomas decreased the number of β-catenin-expressing and Ki67-positive proliferating tumor cells." (PMID 38001599, 2023). "Elevated FOXM1 and MYBL2 is associated with more aggressive meningioma." (PMID 37860270, 2023). "FOXM1 expression is correlated with increased proliferation in meningiomas, and inhibiting FOXM1 using thiostrepton combined with radiotherapy could efficiently kill tumor cells, indicating a novel targeted therapy." (PMID 37248629, 2023). "We speculated that despite being WHO grade I, the short PFS of these meningiomas reflected the aggressive histological features such as high Ki-67 index and high FOXM1 expression." (PMID 35570314, 2022). "Although we posit that supratentorial NF2 meningiomas might have such an aggressive feature as copy number alteration in addition to Ki-67 and FOXM1, it was beyond the scope of this study." (PMID 35570314, 2022). "Similarly, the results obtained in a newly established model of meningioma showed that FOXM1 overexpression increases proliferation in benign meningioma, whereas its depletion decreases proliferation in malignant meningioma." (PMID 35712491, 2022). "Hypermitotic meningiomas had the worst overall survival of all three groups and were distinguished by upregulation of FOXM1 expression, which was found to regulate DNA damage response, potentially increasing hypermitotic meningioma resistance to cytotoxic therapy." (PMID 36686824, 2022). "To test this hypothesis, we performed H&E staining and immunofluorescence for FOXM1 and Ki-67, a marker of cell proliferation, on 13 spatially defined samples from 5 tumors comprising all meningioma grades." (PMID 32968068, 2020). "2D meningioma cells were subdivided into five clusters including proliferating cells expressing the FOXM1 target genes CCNB1 and TOP2A, cells enriched for metabolic pathways, and cells enriched for extracellular matrix organization and integrin interaction pathways." (PMID 32968068, 2020). "This further supports the E2F4/FOXM1 module as a marker of aggressiveness in meningioma." (PMID 33093491, 2020). "Additionally, SLC7A1 may exert oncogenic functions in meningioma by regulating transcription factors FOXM1 and E2F4." (PMID 41184266, 2025). "Similarly, identifying a common transcriptomic change across meningioma allows for treatments to be developed that could prevent or rapidly treat tumour recurrence (e.g. restricting MYBL2 or FOXM1 expression)." (PMID 37860270, 2023). "However, the majority of HM meningiomas did not have any copy number loss of CDKN2A/B or aberrant activation of the FOXM1 pathway." (PMID 36840836, 2023). "Similarly, overexpression of FoxM1 was also found in recurrent meningioma." (PMID 33042832, 2020). "FOXM1 and PRNP were experimentally evidenced to be highly expressed in meningioma cells, and their knockdown hindered cell growth and migration and triggered ROS accumulation." (PMID 41050085, 2025). "Further western blot proved the higher expression of FOXM1 and PRNP in two meningioma cells vs. HMC cells, without significant difference in SEPP1 expression." (PMID 41050085, 2025). "It was noted that most of the oxidative stress-related genes presented differential expression between high-grade and low-grade meningiomas, especially AOX1, FOXM1, GPX3, PRNP, and SEPP1." (PMID 41050085, 2025). "Among the key oxidative stress-related genes, FOXM1 and PRNP were experimentally proven to be up-regulated in two human meningioma cells (CH-157MN and IOMM-Lee) vs. one human meningeal cell (HMC)." (PMID 41050085, 2025).
meningioma (continued). "RNA sequencing analysis revealed a significant decrease in the transcriptional activity of FOXM1 and E2F4 in IOMM-Lee and SZ8511 meningioma cells following SLC7A1 knockdown." (PMID 41184266, 2025). "Altogether, among the key oxidative stress-related genes, FOXM1 and PRNP were experimentally evidenced to be up-regulated in meningiomas." (PMID 41050085, 2025). "Silence of FOXM1 or PRNP effectively attenuated the growth and migration of meningioma cells as well as accelerated intracellular ROS accumulation." (PMID 41050085, 2025). "Western blot confirmed a progressive downregulation of FOXM1 and E2F4 with increasing duration of AZ628 treatment in meningioma cells." (PMID 41184266, 2025). "In our future studies, we will further validate the clinical value of the novel oxidative stress-based classification and the two oxidative stress-related genes (FOXM1 and PRNP) in meningiomas." (PMID 41050085, 2025). "Silence of FOXM1 and PRNP was thus evidenced to induce the excessive accumulation of ROS in meningioma cells." (PMID 41050085, 2025). "Oxidative stress-related genes such as AOX1, FOXM1, GPX3, PRNP, and SEPP1 were differentially expressed between high- and low-grade meningiomas." (PMID 41050085, 2025). "The results revealed a significant reduction of FOXM1 and E2F4 upon SLC7A1 knockdown in meningioma cells." (PMID 41184266, 2025). "In brief, our study demonstrated the tumor-promoting function of SLC7A1 by regulating the transcription factors FOXM1 and E2F4 in meningioma and identified SLC7A1 as a potential therapeutic target." (PMID 41184266, 2025). "This study further experimentally validated the key oxidative stress-related genes: AOX1, FOXM1, GPX3, PRNP, and SEPP1 in human meningeal cells (HMC) and two meningioma cells (CH-157MN and IOMM-Lee)." (PMID 41050085, 2025). "The authors found increased expression of the DREAM complex partners FOXM1 and MYBL2 in those tumors compared to type B meningiomas, resulting in activation of the DREAM complex." (PMID 36937440, 2023). "analyze intratumor heterogeneity suggesting that the loss of chromosome 22q is an early event that tumor evolution, but prove spatially distinct patterns of FOXM1, CDH2, and PTPRZ1 expression providing understanding why meningiomas grow asymmetrically." (PMID 36033542, 2022). "We further identified regional variation in Ki-67 labeling index and FOXM1 immunofluorescence that correlated with tumor grade, with increased heterogeneity among spatially defined WHO grade II and grade III meningioma samples." (PMID 32968068, 2020). "Among these genes, we find that FOXM1, CDH2, and PTPRZ1 are heterogeneously expressed in individual meningiomas." (PMID 32968068, 2020). "Our results revealed for the first time that the overexpression of FOXM1 attenuated the suppressive effect of Merlin on Wnt/β-catenin signaling, thus sensitizing NF2-mutant meningioma cells to ICG-001." (PMID 32642722, 2020). "Interestingly, GSVA analysis at the single-cell level also revealed a significant increase in the transcriptional activity scores of FOXM1 and E2F4 in clusters 4 and 9 of meningioma cells with high SLC7A1 expression." (PMID 41184266, 2025). "Additionally, AZ628 treatment also inhibited the transcriptional activity and protein expression of FOXM1 and E2F4, mirroring the effects of SLC7A1 knockdown in meningioma." (PMID 41184266, 2025). "Moreover, FOXM1 and PRNP were experimentally evidenced as promising treatment vulnerabilities against meningiomas." (PMID 41050085, 2025). "In addition, the bulk-level GSEA analysis also demonstrated a significant upregulation of transcriptional activity for FOXM1 and E2F4 in meningioma samples from the high-SLC7A1 group compared to the low-SLC7A1 group." (PMID 41184266, 2025). "Overexpression of FOXM1 due to the lack of regulation by Merlin promotes meningioma cell proliferation and viability." (PMID 38001599, 2023).
meningioma (continued). "Among meningiomas with GTR, PFS was also different depending on Ki-67 index (Ki-67 ≥ 4 vs. Ki-67 < 4, p = 4.9 × 10–10), FOXM1 protein expression in 111 cases (high vs. low, p = 0.00052), and FOXM1 protein expression in 40 cases of supratentorial NF2 meningioma (high vs. low, p = 0.013)." (PMID 35570314, 2022). "As such, thiostrepton, a FOXM1 inhibitor, combined with radiation therapy, was found to noticeably prevent the proliferation of malignant meningioma cells." (PMID 35712491, 2022). "The expression of FOXM1 itself was increased in high grade meningioma samples relative to WHO grade I tumors, but there was also greater heterogeneity in FOXM1 expression between spatially distinct samples from individual high grade meningiomas compared to grade I tumors." (PMID 32968068, 2020). "Hence, the silence of FOXM1 and PRNP lowered the proliferation and migration of meningioma cells." (PMID 41050085, 2025). "However, overexpressing FOXM1 in transplanted benign meningioma cell lines failed to produce tumors in mice, suggesting that FOXM1 alone was insufficient to drive meningioma growth in vivo." (PMID 38001599, 2023). "FOXM1 has been identified as a key target in meningiomas; however, the role of E2F4 in meningioma has not been previously reported." (PMID 41184266, 2025). "Finally, interfering FOXM1 in CH157-MN cells resulted in decreased sensitivity to ICG-001 treatment, suggesting that ICG-001-mediated growth inhibition of Merlin-negative meningioma cells occurs, at least in part, by attenuating the FOXM1-mediated Wnt/β-catenin signaling." (PMID 32642722, 2020).
neuroblastoma (28 papers, 2009 to 2025). Neuroblastoma (NB) is the most common solid, extracranial childhood tumor. "The results of these in silico analyses should fuel renewed efforts for identifying novel on target compounds to block FOXM1 activation in high-risk neuroblastomas." (PMID 30504901, 2018). "Of tumors common in pediatric oncology, FOXM1 has been implicated in the pathogenesis of neuroblastoma and in medulloblastoma." (PMID 23365673, 2013). "In neuroblastoma cells, CDK4/6 inhibition caused cell-cycle arrest and cellular senescence that was correlated with dose-dependent decreases in phosphorylated RB and FOXM1, respectively." (PMID 33806615, 2021). "Of further interest, re-analysis of published data showed that MYCN transcriptionally activates FOXM1 in neuroblastoma cells." (PMID 30504901, 2018). "Taken together, this experimental analysis further supports the data-mining driven observation that the ESC mRNA gene signature in neuroblastoma cells is enriched for genes that are transcriptionally regulated by FOXM1." (PMID 30504901, 2018). "Collectively, our findings support that the ESC mRNA gene signature in neuroblastoma is also related to patient survival and most interestingly is highly enriched by components of a FOXM1 controlled regulatory network." (PMID 30504901, 2018). "Neuroblastoma is a biologically distinct Pediatric Solid Tumor in which a biologic role for FOXM1 has been recently described." (PMID 23365673, 2013). "A study of malignant neuroblastoma suggested that FOXM1 plays a pivotal role in the tumorigenicity of these aggressive tumor cells via maintenance of their self-renewal capacity." (PMID 24325450, 2013). "Its expression in Ewing tumors is comparable to Neuroblastoma, another childhood solid tumor in which FOXM1 has been studied." (PMID 23365673, 2013). "Our data suggest that targeting TRPM2 may be a novel approach to reduce FOXM1 expression and increase doxorubicin sensitivity in neuroblastoma and other malignancies." (PMID 35428820, 2022). "Last, our study defined for the first time through a cross-species integrative transcriptomics approach putative master regulators for MYCN-driven neuroblastoma tumor development and revealed FOXM1 and the DREAM complex members MYBL2 and E2F8 as top-scoring candidates." (PMID 34638267, 2021). "Furthermore, TBX2 acts as a neuroblastoma core regulatory circuitry component that promotes MYCN/FOXM1-mediated reactivation of DREAM targets, while CLOCK genes are closely associated with cancer development, particularly in endocrine tissues." (PMID 32391054, 2020). "Therefore, we further investigated MYCN controlled regulation of the FOXM1 gene signature in neuroblastoma context." (PMID 30504901, 2018). "Interestingly, the expression of 3 of these genes i.e. MELK, MYBL2 and PLK1 is remarkably highly correlated with FOXM1 expression levels in 200 neuroblastoma tumors (correlation coefficients >0.9) suggesting a very tight co-regulated transcriptional control." (PMID 30504901, 2018). "In neuroblastoma FoxM1 activates SOX2 (Sex determining Y-box 2) expression." (PMID 27074562, 2016). "Interestingly in two malignancies separate from sarcoma, embryonic carcinoma and neuroblastoma, a role for FOXM1 has been identified in the maintenance of the undifferentiated tumor state of the malignant cells." (PMID 27074562, 2016). "Thus, FOXM1 depletion or inhibition in neuroblastoma cells fully recapitulated the phenotype of MEIS2 depletion at both molecular and cellular levels." (PMID 25210800, 2014). "It is known that cells with FOXM1 depletion display mitotic spindle defects, centrosome amplification, chromosome mis-segregation, failure of cytokinesis, and mitotic catastrophe, which are essentially the same phenotypes displayed by neuroblastoma cells with MEIS2 depletion." (PMID 25210800, 2014).
neuroblastoma (continued). "In addition, mouse model studies demonstrated that FOXM1 is involved in maintenance of the carcinogenicity of neuroblastoma cells and the self-renewal capacity of mouse neural stem/progenitor cells via induction of expression of the pluripotency genes Sox-2 and Bmi1." (PMID 24325450, 2013). "Remarkably, the expression of all top 50 correlated genes from the ESC mRNA signature, including FOXM1, increases upon Th-MYCN driven neuroblastoma development." (PMID 30504901, 2018). "We show that TBX2 is a constituent of the recently established core regulatory circuitry in neuroblastoma with features of a cell identity transcription factor, driving proliferation through activation of p21-DREAM repressed FOXM1 target genes." (PMID 30451831, 2018). "Here, the authors investigate the epigenomics and transcriptomics of neuroblastoma, identifying TBX2 as a core regulatory circuitry component enhancing the reactivation of DREAM targets by MYCN/FOXM1." (PMID 30451831, 2018). "A majority of FOXM1 target genes, including CDC25B, CHEK2, CENPA, CENPB, and CENPF, were significantly downregulated in neuroblastoma cells with MEIS2 depletion." (PMID 25210800, 2014). "FOXM1 is a major driver of embryonic stem cell regulatory programs in neuroblastoma patients with MYCN amplified tumors and stage 4 non-amplified tumors, and expression correlates with poor patient outcome and therapy resistance." (PMID 35428820, 2022). "High TRPM2 expression significantly enhanced expression of α1, αv, β1 and β5 integrins in the membrane of neuroblastoma cells and integrin complex formation, through transcriptional mechanisms including increased HIF-1α, E2F1, and FOXM1, resulting in promotion of migration and invasion." (PMID 36446940, 2022). "Since the DREAM complex (B-MYB, FOXM1) have previously been shown to be essential for neuroblastoma cell proliferation and survival, this further suggests that PCLAF plays an important role in neuroblastoma cell proliferation and survival." (PMID 35210406, 2022). "To this end, we compiled a DREAM/FOXM1 signature and could show significant upregulation during TH-MYCN-driven neuroblastoma formation." (PMID 34638267, 2021). "Notably, MEIS2 is a direct transcriptional regulator of FOXM1 and indirect regulator of DREAM expression, warranting further functional studies to further dissect the mechanistic role of MEIS2 during neuroblastoma tumor development." (PMID 34638267, 2021). "Finally, cross-species master regulator analysis identified FOXM1, together with additional hubs controlling transcriptome profiles of MYCN-driven neuroblastoma." (PMID 34638267, 2021). "We downloaded three FOXM1 ChIP-seq experiments conducted on ECC1 (human endometrium adenocarcinoma cell line), MCF-7 (human breast adenocarcinoma cell line), and SK-N-SH (human neuroblastoma cell line) cell lines and visualized them using the Interactive Genomic Viewer (IGV)." (PMID 38338955, 2024). "Importantly, FOXM1 depletion by shRNA significantly abolished the ability of MEIS2d to upregulate the expression of mitotic genes, demonstrating that FOXM1 is an essential mediator of MEIS2 action in neuroblastoma cells." (PMID 25210800, 2014). "Similarly to what is described for N-Myc in neuroblastoma, this Aurora-A function would be independent of its kinase activity in TNBC, since the administration of the Aurora kinase inhibitor VX680 in MDA-MB-231 cells does not cause a reduction in FOXM1 protein levels." (PMID 33981003, 2021). "Increased TRPM2 in tumors may be both a driver of high FOXM1 and the embryonic stem cell program seen in non-MYCN amplified Stage 4 neuroblastoma patients, contributing to increased metastasis and worse outcome." (PMID 36446940, 2022).